NF2 (NF2, moesin-ezrin-radixin like (MERLIN) tumor suppressor)
Diseases named in the same sentence as NF2 in open-access papers (continued):
Sharing a sentence is not in itself a finding about the gene and the disease.
mesothelioma (continued). "This idea is consistent with the absence of reports of increased risk of mesothelioma in NF2 germline mutation carriers." (PMID 37180489, 2023). "Besides NF2, mesotheliomas harbor frequent inactivation of genes of the Hippo pathway, which seems to be an important signaling pathway regulated by merlin in mesothelial cells." (PMID 37180489, 2023). "Another study showed that defactinib sensitivity using mesothelioma cell lines was not related to inactivating NF2 mutations or protein expression of merlin, but was strongly correlated with FAK activity, especially in epithelioid mesothelioma." (PMID 37180489, 2023). "Rapamycin, an mTOR inhibitor, can inhibit proliferation of NF2-altered mesothelioma cells in vitro." (PMID 36138075, 2022). "Preclinical models of mesothelioma confirm that specific alterations can lead to different outcomes, for example, CDKN2A loss leads to poor outcomes and BAP1 alterations in combination with NF2 and CDKN2A/B to rapid disease onset." (PMID 36138075, 2022). "As the most frequent mutations/deletions, the collaborative inactivation of BAP1, NF2, and CDKN2A could result in rapid and aggressive mesothelioma, while homozygous mutation rarely results in carcinogenesis." (PMID 34299035, 2021). "Moreover, NF2 has the overall lowest expression in mesothelioma compared to all other TGCA datasets." (PMID 34621176, 2021). "In mesothelioma, NF2 is found mostly as a biallelic inactivation." (PMID 34249695, 2021). "Parallel evolution involving NF2/-22q implicates a deterministic trajectory in MPM that involves Hippo pathway inactivation, as a key bottleneck during progression of mesothelioma and this is implied in an extreme case whereby NF2 loss occurred 12 years after surgery at the time of progression." (PMID 33741915, 2021). "Then, we also found the NF2 loss is about 45.7% (32/70) of mesotheliomas, and YAP and CDK7 expressions are not correlated with NF2 loss in our mesothelioma TMA array (r = −.093, P = .443; r = −.062, P = .608, respectively) (Tables [Link], [Link], [Link])." (PMID 31755214, 2020). "This might be important in the context of mesothelioma because NF2 alterations, which are frequent in mesothelioma, result in the activation of FAK and mesothelioma cells are sensitive to FAK inhibitors." (PMID 33050791, 2020). "NF2-depleted mesotheliomas are sensitive to the mTOR inhibitor molecule, rapamycin, and thus, a better understanding of the role of NF2 in MPM, may hold pronounced potential for various targeted therapies." (PMID 29342862, 2018). "Furthermore, some studies revealed the involvement of NF2 in the development of malignant plural mesothelioma after asbestos exposure." (PMID 29587439, 2018). "Moreover, CPI-17, a cellular inhibitor of myosin phosphatase targeting subunit 1 (MYPT1-PP1δ), was increased in mesothelioma cells with full-length NF2 compared to normal pleura or mesothelioma with truncated NF2." (PMID 29587439, 2018). "Deleted in around 35–40% of MPM cases and often functionally inactive if present due to somatic mutations, the tumor suppressor, Neurofibromin 2 (NF2) gene, has been implicated as a “gatekeeper” in asbestos-induced mesothelioma tumorigenicity via several mechanisms." (PMID 29342862, 2018). "Among tumor lines with Hippo pathway mutations analyzed by us, one mesothelioma, H2052, with both LATS2 and NF2 mutations, was found to be resistant to XAV939 despite its striking sensitivity to dnTEAD4 inhibition of TEAD-mediated transcription and proliferation." (PMID 27144834, 2016). "Furthermore, we generated a novel murine mesothelioma cell line RN5 originating from an Nf2+/− mouse subjected to repeated crocidolite exposure." (PMID 25877069, 2015). "Thus the expression of the other genes commonly deleted in human mesothelioma, NF2, BAP1 and LATS2 was investigated." (PMID 26680231, 2015).
mesothelioma (continued). "Finally, a novel murine mouse mesothelioma cell line RN5 was generated from a tumor that had developed in a crocidolite-exposed Nf2+/− mouse; this line shows high tumorigenicity in vivo and persistent growth in vitro." (PMID 25877069, 2015). "However, no obvious changes in expression of other genes frequently altered in human mesothelioma such as NF2 and BAP1 was observed in MexTAg tumours." (PMID 26680231, 2015). "The NF2 mutations found in neurofbromatosis 2 differ from the mutations found in mesotheliomas in that mutations in hereditary NF2 are not usually missense mutations." (PMID 24393766, 2014). "Additionally, mesothelioma is characterized by the frequent loss or mutation of tumor suppressor genes such as cyclin dependent kinase inhibitor 2 A (CDKN2A), BRCA1 associated protein 1 (BAP1), neurofibromin 2 (NF2), and cullin 1 (CUL1)." (PMID 40223054, 2025). "Moreover, genetic inactivation of the tumor suppressor NF2, a frequent tumorigenic event in mesothelioma, renders cancer cells more sensitive to ferroptosis, malignant mutations in NF2–YAP signaling can be used to predict the responsiveness of cancer cells to future ferroptosis-inducing therapy." (PMID 37580393, 2023). "First, as NF2 deficiency was previously reported as a biomarker of YAP/TAZ dependency and is frequently found in mesothelioma, we tested GNE-7883 across a panel of NF2-null mesothelioma cell lines and validated that these models are overall responsive to GNE-7883." (PMID 37277530, 2023). "In addition to non-sense/missense mutations or small/large deletions with loss of heterozygosity, resulting in bi-allelic loss of function, other structural abnormalities including gene rearrangement that disrupt the NF2 region can be observed in mesotheliomas." (PMID 37180489, 2023). "Recent genome analysis revealed that NF2 alteration may be a late event in mesothelioma development, suggesting that NF2 mutation confers a more aggressive phenotype to mesothelioma cells and may not be directly caused by asbestos exposure." (PMID 37180489, 2023). "Furthermore, NF2 is a ‘gatekeeper’ in mesothelioma induced by asbestos." (PMID 36553016, 2022). "However, the majority of known TEAD inhibitors only show antiproliferative activities in a few cancer cell lines, such as NF2-mutant mesothelioma, and detailed analysis of TEAD palmitoylation inhibitors in a broad range of YAP-dependent cancer models is still lacking." (PMID 36347861, 2022). "Molecular genetic analysis of mesothelioma revealed frequent copy number loss and recurrent somatic mutations in TSGs such as BRCA1-associated protein 1 (BAP1, 60% of the cases), neurofibromin 2 (NF2, 75% of the cases), and cyclin-dependent kinase inhibitor 2A (CDKN2A, 60% of the cases)." (PMID 34299035, 2021). "We found RASSF7 amplification in 39 mesotheliomas, NF2 mutations in 24, LATS2 mutations in 6 and LATS1 in 2, so that non-overlapping lesions in Hippo pathways were present in 52/121 mesotheliomas (43%) and a further 9 mesothelioma had more than one lesion (total 50%)." (PMID 34580349, 2021). "In addition, research on mesothelioma genome supports the role of inactivated tumor suppressor genes encoded by cyclin-dependent kinase inhibitor 2A (CDKN2A), BRCA1 associated protein 1 (BAP1) and neurofibromin 2 (NF2)." (PMID 32050546, 2020). "The breast cancer cell line MDA-MB-231 and mesothelioma cell line NCI-H2052, cell lines with a known loss of NF2 expression, an upstream negative regulator of YAP, displayed higher phosphorylation of YAP on S127, compared to their counterpart wild-type NF2 cell lines." (PMID 30446657, 2018).
mesothelioma (continued). "In addition to YAP amplification or over expression observed in various epithelial malignancies as well as YAP or TAZ translocations or point mutation, loss of function mutations of core components of the Hippo inhibitory pathway such as LATS, or NF2 are found at high frequencies in mesotheliomas." (PMID 27144834, 2016). "Additionally, our combined approach detected CNV events at other genes associated with mesothelioma: lost copies of LATS1 (associated with hippo signaling) and NF2 (a tumor suppressor) and the amplification of the YAP gene, responsible for encoding a protein that activates transcription factors." (PMID 26185765, 2015). "In addition, mutations in the NF2 gene have been associated with non-neuronal, sporadic cancers such as mesothelioma, suggesting that NF2 has tumor suppressor functions in a variety of tissues." (PMID 24595234, 2014). "Analysis of mesothelioma cell lines and The Cancer Genome Atlas (TCGA) data revealed a significant correlation between OXTR mRNA expression and NF2 gene inactivation." (PMID 40362535, 2025). "Previously in our lab, we derived cell lines from our autochthonous mesothelioma mouse model with genetically defined BNC (Bap1−/−, Nf2−/−, Cdkn2ab−/−) or NC (Nf2−/−, Cdkn2ab−/−) background." (PMID 38519707, 2024). "Therefore, although many NF2 patients reach the age of morbidity for mesothelioma onset, the development of mesothelioma has not specifically been reported, suggesting that NF2 germ line mutation is unlikely to be a predisposing mutation for familial mesothelioma development like BAP1." (PMID 37180489, 2023). "Interestingly, patients and carriers of NF2 familial cancer syndrome do not seem to present a significantly increased risk of mesothelioma, and only a few rare cases of mesothelioma development with constitutional NF2 mutation have been reported so far." (PMID 37180489, 2023). "Incapacitation of any element of the E-cadherin-NF2-Hippo pathway contributes to the expression or activity of its downstream molecule YAP, leaving cancer cells or mutant tumors like NF2- mutant mesotheliomas especially vulnerable to FINs." (PMID 36335094, 2022). "This recapitulates the histological features and gene profile observed in human patients carrying combined BAP1, NF2 and CDKN2A alterations, indicating that the combined deletion of these tumor-suppressor genes creates a mesothelioma-specific microenvironment." (PMID 34830817, 2021). "Clonal positive selection (dN/dS>1) involved five tumour suppressors NF2, BAP1, SETD2 which were independently validated in the mesothelioma TCGA7, FBXW7 and PRELID1." (PMID 33741915, 2021). "Studies have also revealed a loss of and/or mutations for several components of the Hippo pathway (e.g., YAP, NF2, LATS2, and RASSF1) in mesothelioma." (PMID 30965570, 2019). "Primary mesothelial cells from WT and Nf2+/− mice grown in DMEM showed the typical cobblestone-like morphology similar as, e.g., the human mesothelioma cell line ZL55 consisting of cells with an epithelioid morphology used in previous studies." (PMID 25877069, 2015). "Allelic losses at three known tumour suppressor regions (22q which includes Nf2 marker (NF2CA3), 9p for the p16 gene, and 3p for FHIT gene) and at other areas of 14q and 6q, are also frequent in mesothelioma." (PMID 23516439, 2013). "Preclinical studies have demonstrated that mesothelioma cells lacking NF2 are sensitive to inhibitors of focal adhesion kinase (FAK), which disrupts the interaction of FAK with SRC and the p85 regulatory subunit of PI3K." (PMID 40362535, 2025).
mesothelioma (continued). "While these synthetic agents effectively delayed tumor onset in asbestos-exposed Nf2+/−;Cdkn2a+/− mice, mesothelioma was not prevented." (PMID 38784478, 2024). "Notably, NF2 and KRAS are mutually exclusive, indicating that these genes interact to participate in mesothelioma tumorigenesis." (PMID 38879686, 2024). "Notably, inactivation of Hippo pathway components NF2 and LATS1/2 are common in mesothelioma and result in constitutive activation of the YAP1/TAZ transcriptional coactivators, thereby conferring malignant phenotypes to mesothelial cells." (PMID 38784478, 2024). "Further studies must be conducted to elucidate the specific pathway involved in cancer formation in NF2-mutant mesotheliomas, be it the Hippo signaling cascade, BCR, neither, or both." (PMID 39796693, 2024). "To investigate whether a combined treatment of EZH2 and FGFR inhibition is effective, we made use of mouse mesothelioma cell lines derived from our genetically defined BNC (Bap1−/−, Nf2−/−, Cdkn2ab−/−) and NC (Nf2−/−, Cdkn2ab−/−) mice." (PMID 38054839, 2024). "Similar triple-knockout mouse models also confirmed that, although Bap1 deletion alone did not induce mesothelioma, Bap1 deletion dramatically accelerated mesothelioma development with the combined disruption of Nf2 and Cdkn2ab." (PMID 37180489, 2023). "Absence of typical mesothelioma NF2 and BAP1 driver events argued against a mesothelioma, and subsequent negative H3K27me3 staining further strengthened the diagnosis of sarcoma." (PMID 35053600, 2022). "Although not investigated, this may correspond to differences in tumour growth seen in mesothelioma mouse models where co-alterations of BAP1, NF2 and CDKN2A/B led to a faster tumour growth compared to tumours with alterations in only one or two genes." (PMID 36138075, 2022). "Based on our data, targeted treatments might also become a possible approach for mesothelioma, as alterations in hedgehog pathway-related genes (e.g., PTCH1/2 and SUFU) and hippo pathway-related genes (particularly NF2) were found." (PMID 36138075, 2022). "Our testing of primary cells revealed micromolar responsiveness of mesothelioma to the YAP inhibitor Verteporfin, although it did not seem to depend on the presence of NF2 or other Hippo mutations." (PMID 34580349, 2021). "The lack of NF2 tumor suppressor gene, coding for Merlin protein, is a frequent event in mesothelioma." (PMID 28848709, 2017). "In addition, we validated the statistical deregulation of 66 genes out of the selected 117, among which there were several well-known mesothelioma genes, such as MSLN, BAP1, and NF2." (PMID 27835874, 2017). "Clinically relevant markers of mesothelioma, transcriptional and metabolic profiles, as well as status of the tumor suppressor genes CDKN2A and NF2, the ‘gatekeeper' in MM development, were examined in the primary cell lines and compared with those of two widely used commercial cell lines." (PMID 26891694, 2016). "Transduction of the NF2 gene in mesothelioma has not been examined probably due to the complexity of the downstream pathways." (PMID 23484132, 2013).
mesothelioma (continued). "Even if mesothelioma is not a distinctive feature of NF2-SWN, a high prevalence of mesothelioma in NF2-SWN could nevertheless escape detection because both diseases are rare." (PMID 40725095, 2025). "In NF2-mutant settings, FAK inhibition can attenuate YAP/TAZ activity and favor hippo output, leading to downregulation of YAP target genes and induction of apoptosis - especially under high extracellular matrix stiffness or anchorage independent growth, as shown in mesothelioma models." (PMID 41487565, 2025). "As for NF2, although many NF2 patients reach the age of morbidity for mesothelioma onset, the development of mesothelioma has not specifically been reported, suggesting that NF2 germline mutation is unlikely to be a predisposing condition for familial PM development like BAP1." (PMID 40725095, 2025). "Despite blocking a broad spectrum of Cullin–RING E3 ligases including CRL4DCAF1, NF2–NAE inhibitors could be a promising target for therapeutic intervention in patients with merlin-negative mesothelioma." (PMID 29587439, 2018). "TRAF7 was enriched in WDPMT, while common mesothelioma alterations (BAP1, NF2, CDKN2, and SETD2) were absent." (PMID 39167353, 2024). "In recent studies, NF2 and LATS2, both belonging to the hippo pathway, were identified as key drivers for non-asbestos-related tumorigenesis for mesothelioma, although both also play a role in patients with mesothelioma who were exposed to asbestos." (PMID 35205798, 2022).